UCP3 (uncoupling protein 3)
Diseases named in the same sentence as UCP3 in open-access papers (continued):
Sharing a sentence is not in itself a finding about the gene and the disease.
type 2 diabetes (19 papers, 2006 to 2025). "In humans, genetic variations of Ucp2 and Ucp3 have been associated with abdominal obesity, type 2 diabetes, and increased serum lipid levels." (PMID 32452516, 2020). "Thus, the data accumulated so far suggest that type 2 diabetes inhibits UCP3 expression in myocytes, thereby leading to partial UCP3 protein deficiency in the heart." (PMID 30374710, 2018). "Through targeted mutation of one UCP3 gene copy in rats, we showed that partial myocardial UCP3 deficiency, resembling that which occurs with type 2 diabetes, was sufficient to severely impair the contractile recovery of ex vivo perfused hearts subjected to I/R." (PMID 30374710, 2018). "In humans, the expression of the Ucp3 gene in skeletal muscle and pancreas of diabetic patients is decreased, suggesting Ucp3 involvement in the development of type 2 diabetes." (PMID 35323702, 2022). "In prediabetic subjects and type 2 diabetic patients, skeletal muscle UCP3 content is decreased by almost 50%." (PMID 30374710, 2018). "Regulation of myocardial UCP3 with hyperinsulinemia and type 2 diabetes is less clear with reports of either unchanged, increased, or decreased expression, in the rodent models explored so far." (PMID 30374710, 2018). "Our previous meta-analyses indicate that the UCP2 Ala55Val and UCP3 -55C/T polymorphisms are type 2 diabetes susceptibility loci in populations of Asian, but not European descent." (PMID 23560041, 2013). "However, the impact of type 2 diabetes on myocardial UCP3 expression has remained controversial." (PMID 30374710, 2018). "In contrast, further results indicate that the UCP2 Ala55Val and UCP3 -55C/T polymorphisms may indeed be risk factors for susceptibility to type 2 diabetes in individuals of Asian descent, but not in individuals of European descent." (PMID 23537071, 2013). "On the other hand, decreased expression of UCP-3 in high glucose concentrations may impair beta-cell function, implicating that mechanisms that increase UCP-3 expression and/or function are potential therapeutic targets to offset defects of insulin secretion in humans with type-2 diabetes." (PMID 18167556, 2008). "The Plasma Metabolome in Overweight Type 2 Diabetes Mellitus (T2DM) vs. Non-Diabetic Subjects with or without an Uncoupling Protein 3 (UCP3) Missense Mutation Reveals Novel Metabolite Signatures Reflective of Genotype and Diabetic Status." (PMID 21170321, 2010). "Therefore, low UCP-3 levels may contribute to the pathogenesis of type-2 diabetes." (PMID 18167556, 2008).
heart failure (8 papers, 2011 to 2023). Inability of the heart to pump blood at an adequate rate to meet tissue metabolic requirements. "Moreover, downregulation of UCP-3 in rats that is associated with doxorubicin chemotherapy-induced heart failure improves efficiency of cardial ATP synthesis at an expense of increased mitochondrial ROS formation." (PMID 26304588, 2015). "In ischemic heart, the genetic deletion of UCP3 leads to heart failure by exacerbating apoptotic cell death." (PMID 27642497, 2016). "Recently, UCP2 was shown to be upregulated in an aortic regurgitation model of heart failure, and UCP3 upregulation and mitochondrial uncoupling were demonstrated in viable myocardium of chronically infarcted, failing rat hearts." (PMID 22125598, 2011). "The genes that were most highly expressed in only a single-cell type were Gm20658 (fibroblasts), Ucp3 (cardiomyocytes), Spock2 (endocardial cells), Irf7 (endothelial cells), and Ifi206 (macrophages), of which Ucp3 and Irf7 were involved in heart failure and pathological cardiac hypertrophy." (PMID 37010266, 2023). "Heart failure results in a decrease in Ucp2 and Ucp3, though it is unknown whether the change in these proteins is beneficial or detrimental to the failing heart; however, an increase in the expression of UCPs in cardiac mitochondria decreases free radical production." (PMID 33287280, 2020). "Taken together, our results suggest that HK can increase the expression of the cardioprotective protein Ucp3 and maintain MMP, thereby inhibiting the production of ROS after MI and ameliorating heart failure." (PMID 35264952, 2022). "In animal model of heart failure induced by pressure overload induced by constriction of the ascending aorta, the expression of UCP2 and UCP3 is downregulated and an increase of ROS generation is enhanced to induce cardiac cell hypertrophy." (PMID 27642497, 2016). "Here, we observe a similar effect of GLP-1 infusion on UCP-3 and MCO and also observe better preservation of these components following rapid pacing in old animals without baseline heart failure." (PMID 25078106, 2014).
Hepatic steatosis (7 papers, 2009 to 2024). Steatosis is a term used to denote lipid accumulation within hepatocytes. "UCP gene expression is increased in hepatic steatosis and evidence supports a role for UCP3 in fatty acid metabolism by exporting fatty acid anions, and thus maintaining mitochondria CoA levels." (PMID 20300478, 2009). "Thus, the increase in ACSLV and UCP3 proteins in hepatic steatosis is an adaptive protective mechanism to prevent mitochondrial lipotoxicity." (PMID 20300478, 2009).
Hyperglycemia (7 papers, 2008 to 2026). An increased concentration of glucose in the blood. "Hyperglycemia alone, i.e., in an insulin deficient and non-obese context, has been shown to rapidly increase cardiac expression of Pdk4 and Ucp3, and to provoke metabolic inflexibility and cardiac dysfunction in mice." (PMID 37626210, 2023). "Increased expression of UCP-2 and decreased expression of UCP-3 in humans with chronic hyperglycemia may contribute to impaired glucose-stimulated insulin secretion." (PMID 18167556, 2008). "Specific supplementation of leucine in drinking water prevented hyperglycemia and decreased weight and fat gain from high‐fat diet feeding in mice, not by decreasing energy intake but by increasing resting energy expenditure and UCP3 (uncoupling protein 3) expression in adipose and muscle." (PMID 35526271, 2022).
metabolic syndrome (7 papers, 2009 to 2021). A cluster of metabolic risk factors for CARDIOVASCULAR DISEASES and TYPE 2 DIABETES MELLITUS. "This study provides new evidence concerning associations between genetic variations in the UCP2 and UCP3 genes and serum lipid concentrations as well as indices of abdominal obesity, both being characteristics of the metabolic syndrome." (PMID 19769793, 2009). "However, this acute exercise performed by metabolic syndrome patients reduces the gene expression of CoxIV and Tfam and maintains the basal expression of MitoND5, UCP3, HO1, MnSOD, GPx, CAT, Mfn1, Mfn2, Nrf2 and PGC1α." (PMID 34198661, 2021). "Our study reveals that expression of UCP2, but not UCP3, is lower in the skeletal muscle of ATX mice, suggesting that ROS production is favoured under dyslipidemia and that oxidative stress is more prone to happen." (PMID 27010651, 2016).
Impaired glucose tolerance (6 papers, 2008 to 2019). An abnormal resistance to glucose, i.e., a reduction in the ability to maintain glucose levels in the blood stream within normal limits following oral or intravenous administration of glucose. "UCP3 protein content is reduced in prediabetic subjects (i.e., impaired glucose tolerance) and DM2, and eight weeks of rosiglitazone treatment significantly increases insulin sensitivity and restores skeletal muscle UCP3 protein in diabetic patients." (PMID 23841103, 2013). "UCP-3 protein levels were lower in skeletal muscle of prediabetic (impaired glucose tolerance) and type-2 diabetic subjects compared to healthy control subjects." (PMID 18167556, 2008).
ischemia (6 papers, 2013 to 2020). A hypoperfusion of the BLOOD through an organ or tissue caused by a PATHOLOGIC CONSTRICTION or obstruction of its BLOOD VESSELS, or an absence of BLOOD CIRCULATION. "In rats rendered insulin resistant by high-sucrose feeding, we observed a similar decrease in cardiac UCP3 levels that was associated with decreased rates of myocardial LCFA oxidation after ischemia and impaired recovery of contractile function." (PMID 30374710, 2018). "Moreover, our data confirm that partial UCP3 deficiency is sufficient to impair contractile recovery of the rat heart post ischemia, which is linked to mitochondrial dysfunction and decreased capacity to oxidize LCFAs at reperfusion." (PMID 30374710, 2018). "But while cardiac power from ucp3+/+ hearts recovered to near-baseline values following 15 min of total global normothermic ischemia, hearts from ucp3+/− animals experienced a rapid and sustained impairment in contractile function at reperfusion." (PMID 30374710, 2018). "Time to recovery of aortic pressure post ischemia also tended to increase for the ucp3+/− hearts (p = 0.08)." (PMID 30374710, 2018). "Following ischemia, the contractile function of ucp3+/+ hearts perfused with octanoate recovered completely although the time to recovery of aortic pressure tended to increase in comparison to hearts perfused with oleate (249 ± 90 vs. 89 ± 17 s; p = 0.08)." (PMID 30374710, 2018). "At the functional level, MCFA supplementation promoted complete recovery of contractile function for ucp3+/− hearts following ischemia." (PMID 30374710, 2018). "Following ischemia, contractile recovery of ucp3+/+ hearts was complete and sustained over the whole reperfusion period, although the recovery of aortic pressure was still delayed when compared to oleate (190 ± 33 vs. 89 ± 17 s; p = 0.01)." (PMID 30374710, 2018). "UCP3 is expressed in response to reperfusion after ischemia and, activating a mechanism cytoprotective antioxidant, it is capable of reducing the production of ROS and subsequent reperfusion injury." (PMID 25103673, 2014). "Ucp2 and Ucp3 also dissipate the mitochondrial electrical potential, but do so in order to reduce the production of the superoxide radicals at complex I in the setting of ischemia." (PMID 33287280, 2020). "Octanoate was readily oxidized by the ucp3+/+ hearts before and after ischemia." (PMID 30374710, 2018). "Moreover, the burst of ROS generated post-ischemia by ucp3+/− mitochondria was attenuated when compared to ucp3+/− mitochondria supplied with oleate alone, so that ROS levels were now comparable to that produced by ucp3+/+ mitochondria." (PMID 30374710, 2018). "Based on this evidence, we hypothesized that UCP3 deficiency is responsible for impairment of myocardial LCFA oxidation at reperfusion, thereby causing energetic deficiency and impairment of contractile recovery post ischemia." (PMID 30374710, 2018). "We also found a negative remodeling of the left ventricle in response to ischemia in mice leaking UCP3, confirming the cardioprotective role of this protein." (PMID 25103673, 2014).
Sepsis (5 papers, 2010 to 2025). Sepsis is defined as life-threatening organ dysfunction caused by a dysregulated host response to infection. "Uncoupling proteins (UCPs) have been implicated in sepsis where UCP3 has been shown to be upregulated in muscle in a CLP model in rats and UCP2 deficient mice were protected from LPS-induced liver failure." (PMID 21106065, 2010). "In response to sepsis, upregulation of uncoupling protein 3 (UCP3) has been seen in mouse skeletal muscle, whilst UCP3 expression is also elevated in human muscle in response to redox stress following shorter-term hypoxic exposure." (PMID 40061448, 2025). "In this model of early sepsis, UCP3 expression was still high in the cardiac mitochondria of animals treated with EPA." (PMID 31534623, 2019). "Furthermore, increased muscle expression of UCP3 has been postulated to modulate oxidative stress and lipotoxicity in a rat model of cachexic sepsis." (PMID 36499637, 2022). "Moreover, the physiological significance of any UCP3-mediated uncoupling is unclear, since in a mouse model of sepsis, survival rates were not different between wild-type and UCP3 knockout mice." (PMID 40061448, 2025).
coronary artery disease (4 papers, 2013 to 2023). "The Russell group and the Esposito group demonstrated a cardioprotective role for UCP3 for ischemic heart disease." (PMID 30374710, 2018). "These beneficial effects could be related to the ability of ucp3 to promote mitochondrial uncoupling and control ROS production and suggest that uncoupling proteins might represent novel therapeutic targets in patients with coronary artery disease." (PMID 23688674, 2013).
Hypertension (4 papers, 2011 to 2022). The presence of chronic increased pressure in the systemic arterial system. "The observations of comparable changes in Ucp3 expression in RVLM of young and adult animals to systemic l-NAME treatment are interpreted to suggest a minor role of mitochondrial Ucp3 in RVLM on age-related susceptibility to hypertension in adult rats to systemic NO deficiency." (PMID 36140333, 2022). "We also examine the interactions of UCP2/UCP3 with adiposity and hypertension for prediabetes and T2DM." (PMID 29529994, 2018).
myocardial infarction (4 papers, 2013 to 2022). Gross necrosis of the myocardium, as a result of interruption of the blood supply to the area, as in coronary thrombosis. "In mice, genetic UCP3 deletion was associated to decreased myocardial ATP content, as well as worsening of cardiac function, increased cardiomyocyte death, and greater mortality after myocardial infarct." (PMID 32493392, 2020). "After myocardial infarction, LV fractional shortening was significantly lower (p < 0.05) in both WT (42.7 ± 3.1%) and UCP3−/− (24.4 ± 2.5%) mice compared to sham-operated animals." (PMID 25103673, 2014). "At separate analysis, after myocardial infarction SUV was significantly higher in remote areas than in infarcted territories in both UCP3−/− and WT mice." (PMID 25103673, 2014). "After myocardial infarction SUV was significantly higher in remote areas than in infarcted territories in both UCP3−/− and WT mice (both p < 0.01)." (PMID 25103673, 2014). "After myocardial infarction, LV volume was higher in both WT (59.9 ± 9.3 μl) and UCP3−/− (75.5 ± 10.8 μl) as compared to sham animals, with UCP3−/− mice showing the highest values." (PMID 25103673, 2014). "After myocardial infarction, LV fractional shortening was significantly lower compared to sham-operated mice in both WT and UCP3−/− mice." (PMID 25103673, 2014). "Cardiac 18F-FDG PET/CT was performed in UCP3 knockout (UCP3−/−) and wild-type (WT) mice one week after induction of myocardial infarction or sham procedure." (PMID 25103673, 2014). "More recent evidences suggest that UCP3 genetic deletion promotes mitochondrial dysfunction, and increases ROS production and apoptotic cell death after myocardial infarction in mice, enlarging infarct size and accelerating heart failure." (PMID 25103673, 2014). "After myocardial infarction, SUV was higher in both WT (2.2 ± 0.6) and UCP3−/− (4.0 ± 0.9) compared to sham animals, with UCP3−/− mice showing the highest values." (PMID 25103673, 2014). "Noteworthy, UCP3−/− mice showed the highest value of SUV and the results of two-way analysis of variance demonstrated a significant interaction between genotype and myocardial infarction." (PMID 25103673, 2014). "On the other hand, after myocardial infarction SUV in remote areas was higher in both WT and UCP3−/− compared to sham animals." (PMID 25103673, 2014). "However, in non-cardiac tissue SUV was independent from UCP deletion and myocardial infarction, indicating that blood tracer availability for myocardial uptake was not altered in UCP3−/− mice." (PMID 25103673, 2014).
Abdominal obesity (3 papers, 2009 to 2020). Excessive fat around the stomach and abdomen. "In Caucasoid and Indian populations, the UCP3 -55(rs1800849) T allele was associated with abdominal obesity,meanwhile in Asian population the C allele present in theCGTACC haplotype was associated with this condition." (PMID 29786102, 2018).
cardiac arrhythmia (3 papers, 2018 to 2024). Any disturbances of the normal rhythmic beating of the heart or MYOCARDIAL CONTRACTION. "A cardioprotective role for UCP3 has also been demonstrated, with mice deficient in UCP3 being more susceptible to acute myocardial I/R injury, and cardiac arrhythmias." (PMID 32490600, 2020). "Among the four genes, UCP2, UCP3, and CPT2 played a crucial role in fatty acid oxidation, it has proven that the downregulation of UCP2 and UCP3 impaired myocardial fatty acid oxidation and elevates the production of reactive oxygen species (ROS), subsequently increasing the incidence of arrhythmia." (PMID 38283583, 2024).
Cachexia (2 papers, 2011 to 2023). Severe weight loss, wasting of muscle, loss of appetite, and general debility related to a chronic disease. "The upregulation of UCP-2 and UCP-3 was found to contribute to skeletal muscle loss during cancer cachexia, although some studies indicated that the upregulation of UCPs does not have any direct effect on skeletal muscle loss." (PMID 36900198, 2023). "Ouraccompanying whole-genome expression experiments complemented our NMR findings, revealingaberrant expression of genes involved in mitochondrial biogenesis (PGC-1ß), anduncoupling (UCP3) in a clinically relevant cancer cachexia model." (PMID 21069263, 2011).
cardiac hypertrophy (2 papers, 2019 to 2023). "Mitochondrial uncoupling protein 3 (UCP3) exerts an anti-OS function by activating FGF21 under myocardial hypertrophy condition." (PMID 31498116, 2019).
Cardiac Ischemia (2 papers, 2013 to 2016). "Taken together, these data suggest that ucp3 levels regulate cell survival and infarct size after acute MI by modulating mitochondrial structural and functional adaptations to myocardial ischemia." (PMID 23688674, 2013).
cardiomyopathy (2 papers, 2013 to 2025). A disease of the heart muscle or myocardium proper. "The same was observed for PDK4 and UCP3, genes that exacerbate cardiomyopathy." (PMID 23593350, 2013).
clear cell renal cell carcinoma (2 papers, 2015 to 2016). "Finally, UCP3 has been linked to clear cell renal cell carcinoma: it has been proposed that inhibition of UCP3 by ADP might contribute to the setting of the endogenous mitochondrial membrane potential." (PMID 27289382, 2016). "Finally, UCP-3 protein abundance of PT-derived clear cell renal cell carcinoma and normal renal tissue was compared in human specimens indicating upregulation of UCP-3 during tumor development." (PMID 26304588, 2015). "Finally, to estimate whether this in vitro finding might be translated to the in vivo situation, the present study analyzed UCP-3 expression in PT-derived clear cell renal cell carcinoma demonstrating marked up-regulation of UCP-3 by the tumor cells." (PMID 26304588, 2015).
ovarian carcinoma (2 papers, 2020 to 2022). A malignant neoplasm originating from the surface ovarian epithelium. "The survival analysis revealed that highly expressed UCP1, UCP2, UCP3 and UCP5 were associated with longer OS, PPS and PFS in patients with ovarian cancer." (PMID 35090503, 2022). "In addition, ovarian cancer patients at Stage 3 and Grade 2, 3 were predicted to have longer OS when they have higher mRNA levels of the UCP3." (PMID 35090503, 2022). "Ovarian cancer patients with high mRNA levels of UCP2 and UCP3 were predicted to have improved OS and PFS (p < 0.05)." (PMID 35090503, 2022). "UCP2 and UCP3 protein expression increased during ovarian cancer progression and after aggregation in comparison to the MOSE-E with a significant increase in UCP3 for the adherent MOSE-L and MOSE-LTICv spheroids (p<0.05)." (PMID 33520711, 2020). "In addition, we also found that UCP3 is positively correlated with both cell infiltration and cell markers of regulatory CD8+ cells, a tumor suppressor cell, indicating that UCP3 may participate in the progression of ovarian cancer by regulating the infiltration of CD8+ cells." (PMID 35090503, 2022).